USP17L13 (ubiquitin specific peptidase 17 like family member 13)
Description:
Deubiquitinating enzyme that removes conjugated ubiquitin from specific proteins to regulate different cellular processes that may include cell proliferation, progression through the cell cycle, apoptosis, cell migration, and the cellular response to viral infection.
Tractability: No criterion of Open Targets' tractability assessment is met for any kind of drug.
Gene: Protein-coding gene on chromosome 4 (9,224,896 to 9,226,488, forward strand). Ensembl gene ENSG00000232399.
Subcellular location: Nucleus; Endoplasmic reticulum
Pathways (Reactome):
Metabolism of proteins: Ub-specific processing proteases
Gene Ontology:
Molecular function: cysteine-type deubiquitinase activity
Biological process: regulation of apoptotic process; protein deubiquitination
Cellular component: endoplasmic reticulum; nucleus
Homologues: Paralogues in human: USP17L17 (99% identical), USP17L11 (98% identical), USP17L19 (98% identical), USP17L20 (98% identical), USP17L22 (98% identical), USP17L24 (98% identical), USP17L25 (98% identical), USP17L26 (98% identical), USP17L27 (98% identical), USP17L28 (98% identical), USP17L29 (98% identical), USP17L30 (98% identical), and 59 more.
Diseases named in the same sentence as USP17L13 in open-access papers:
USP17L13 is named in the same sentence as 2 diseases in open-access papers, as found by Europe PMC text mining. Sharing a sentence is not in itself a finding about the gene and the disease.
USP17L13 shares sentences with these, for which no sentence is quoted: influenza (1 paper); viral infection (1).